BCL2 (BCL2 apoptosis regulator)
Diseases named in the same sentence as BCL2 in open-access papers (continued):
Sharing a sentence is not in itself a finding about the gene and the disease.
tumor (continued). "SSTR2-mediated regulation of tumour growth is further supported by the receptor-induced activation of caspase-8 and post-transcriptional downregulation of antiapoptotic protein Bcl-2, as well as the upregulation of TNFα and TRAIL receptors." (PMID 38203605, 2023). "Survival is statistically significantly affected by age and stage of the disease (results not shown), and without significance, survival is associated with the histological type of tumor, Ki-67 tumor proliferative capacity, VEGF and Bcl-2 expression." (PMID 36766867, 2023). "Formononetin can inhibit tumor cell proliferation by inducing cell cycle arrest and induce cell apoptosis by regulating Bax, Bcl-2, and caspase-3 proteins." (PMID 37799727, 2023). "Meanwhile, HOTAIR can inhibit tumor cell apoptosis via the Bax/Bcl-2 pathway by promoting the expression of related protein Bcl-2 and inhibiting the expression of proto-oncogene Bax." (PMID 36924407, 2023). "Research has shown that inhibition of BCL2 regulates the M2 macrophage depolarization, which promotes anti-cancer immunity and interferes with tumor progression." (PMID 37770477, 2023). "The downregulation of cyclin D1 and the anti‐apoptotic Bcl2 is in line with a reduction of the rate of tumour cell proliferation and induction of apoptosis, respectively." (PMID 37390227, 2023). "B-cell lymphoma-2 (BCL-2) gene was initially regarded as a growth-driven oncogene and was later identified to promote tumor cell survival by inhibiting apoptosis." (PMID 37592239, 2023). "In a direct comparison of cisplatin-resistant cells we identified a prominent loss of sensitivity to BCL2/BCL-XL inhibitors that is associated with an increase in MCL1 dependency and high expression of MCL1 in patient tumour tissues." (PMID 37723317, 2023). "Production of IFN-γ has widespread effects within the tumor, causing recruitment of immune cells and induction of apoptosis through FAS ligand and Bcl2 pathways." (PMID 37514190, 2023). "In comparison to tumor tissue homogenate, a reduction in Bcl-2 level was seen after 100 μl of S. cerevisiae-GNSs treatment (P ≤ 0.01)." (PMID 36877301, 2023). "In vivo cell apoptosis was evaluated by detecting Bax and Bcl-2 expression in tumor tissues via immunohistochemical and western blot analyses." (PMID 36852267, 2023). "We also established significant (p < 0.05) correlations of DKI with Ki-67 labeling index and Bcl-2 expression activity in highly perfused enhancing tumor core and in perifocal infiltrative edema zone." (PMID 37345097, 2023). "Together, these studies identify a promising therapeutic strategy for KRAS-mutant NSCLCs, demonstrate that BCL-2 proteins are the key mediators of the therapeutic response in this tumor type, and uncover a predictive biomarker of sensitivity." (PMID 37384411, 2023). "BCL-2 has been reported to inhibit tumor cell apoptosis induced by chemotherapy drugs by reducing the permeability of the mitochondrial membrane and maintaining its integrity." (PMID 37674118, 2023). "This modification resulted in the upregulation of BCL-2 expression, thereby promoting cell proliferation, inhibiting apoptosis, and promoting tumor growth." (PMID 36673448, 2023). "As one putative resistance mechanism occurring in vivo, we identified the upregulation of the pro-survival protein Bcl-2 which was upregulated upon Regorafenib exposure during the phase of early tumor development." (PMID 37620408, 2023). "Previous studies of Nur77 translocation also demonstrated that Nur77 can induce apoptosis of tumor cells, cardiomyocytes, and other cells via binding to Bcl-2 on mitochondria." (PMID 37405051, 2023). "We demonstrate that heightened BCL-2 family protein phosphorylation modulated the apoptotic protein interactome and altered tumor cell survival dependence from BCL-2 to MCL-1, thus diminishing the sensitivity of malignant lymphoid cells to venetoclax." (PMID 37751299, 2023).
tumor (continued). "FOXO1 has tumor-suppressive properties and induces apoptosis by suppressing Bcl-2 and promoting Bax activity." (PMID 37438760, 2023). "miR-29b can also significantly inhibit BCL-2 expression and upregulate Bax expression, promoting tumor cell expression." (PMID 37670948, 2023). "BCL2 on the other hand is recognized as an anti-apoptotic molecule, noted to be upregulated in tumour cells." (PMID 38022682, 2023). "Accordingly, BCL-2 has been recognized as a valid therapeutic target for restoring apoptosis in chemotherapy-resistant tumor cells." (PMID 37894324, 2023). "More recently, miR-190b has been shown to have a capacity for inhibiting tumor cell proliferation and promoting apoptosis via Bcl-2 regulation." (PMID 37720343, 2023). "Research on different tumour tissue is necessary to figure out the mechanisms regulating the influence of miR-210 on Bcl-2." (PMID 36939902, 2023). "A significant elevation in the mRNA expression of Bcl2 (p = 0.0455) and ki67 (p = 0.0298) in U87-R tumor cells, as quantified by qRT PCR, was observed." (PMID 36840009, 2023). "Our data revealed that DMF was able to downregulate BCL-2 expression, by increasing the sensitivity of tumor cells to programmed cell death." (PMID 36769105, 2023). "The induction of apoptosis was also confirmed by the ratio of the expression levels of the BAX and BCL-2 genes, which was higher than 1 in tumor cells treated with CIMVs-TRAIL." (PMID 36661524, 2023). "The IHC results showed that RP4 significantly decreased the levels of Ki67 and Bcl2, indicating that tumor cell proliferation was inhibited by RP4." (PMID 36986805, 2023). "The concomitant inhibition of the BCL-2 protein by venetoclax results in the simultaneous targeting of all three anti-apoptotic proteins, thereby yielding in vivo anti-tumor activity achievable with clinically attainable doses." (PMID 37958832, 2023). "BCL-2 dependence in solid tumors is considered an important factor for tumor relapse and drug resistance." (PMID 37894324, 2023). "Only in the case of miR-16-5p one of our selected oncogenes, BCL2, has been experimentally verified as a target, providing a partial explanation of the tumor suppressive potential of this miRNA." (PMID 37628629, 2023). "The upregulation of anti‐apoptotic Bcl‐2 members through signalling pathways within the tumor microenvironment appears as a major factor leading to resistance to venetoclax." (PMID 36550750, 2023). "In the current study, 1 patient with NOTCH1-activating metastatic ACC and tumor BCL2 overexpression had additional tumor growth stabilization with the off-label addition of the BCL2 inhibitor Venetoclax to CB-103 after first progression." (PMID 37712875, 2023). "At a concentration of 50 μM, polydatin was shown to reduce tumor cell proliferation and colony formation via enhancing the Bak/Bcl-2 ratio in A549 and NCI-H1975 cell lines." (PMID 37568796, 2023). "Bcl-2 is considered as an inducer of angiogenesis, which can promote tumor vascular network formation and further afford nutrients and oxygen to promote tumor progression." (PMID 37237269, 2023). "Again, these results were specific, as IgG treatment remained unable to decrease the levels of phospho-BAD and Bcl-2 in the tumor tissues of PDX mice." (PMID 38136341, 2023). "F16 is inherently cytotoxic, targeting tumor cell mitochondria to induce apoptosis and inducing tumor cell necrosis in the presence of anti-apoptotic Bcl-2 protein overexpression, with dual efficacy in killing tumor cells." (PMID 36765624, 2023).
tumor (continued). "Tumor cell survival and apoptosis is regulated by the balance between pro-apototic Bcl-2 proteins (Bax, Bad, and Bid) and anti-apoptotic proteins (Bcl-2 and Bcl-xL)." (PMID 37091854, 2023). "The effect of leptin on tumor progression relies on the increased expression of antiapoptotic proteins, such as Bcl-2 and Bcl-xl, which suppress the programmed cell death of breast cancer cells." (PMID 37509120, 2023). "Apatinib can inhibit the VEGFR2/STAT3/Bcl-2 signaling pathway and increase the expression of beclin-1 in vivo, thereby inducing autophagy and apoptosis of tumor cells." (PMID 37124541, 2023). "It has now been shown that the pre-sensitization of B-acute lymphoblastic leukemia (B-ALL) tumor cells with the BCL-2 inhibitor venetoclax can up-regulate the expression of CD19 and pro-apoptotic proteins on tumor cells." (PMID 37298069, 2023). "while the changes of tumor promoting factors Bcl-2, CyclinD1 and VEGF, downstream proteins regulated by NF-κB, were all consistent with phosphorylation of NF-κB p65 in C-LCs of each group." (PMID 37013587, 2023). "Many cytotoxic cancer drugs depend on BAX/BAK-dependent mechanisms to facilitate their anti-tumor effects, and upregulation of BCL-2 anti-apoptotic proteins facilitates resistance to several chemotherapies." (PMID 39872303, 2023). "The combinational drugs synergistically caused a significant imbalance in Bax/Bcl-2, and led to increased levels of caspase-3, caspase-9 and PARP-1, ultimately resulting in potent tumor suppression in BGC823 cell-xenografted mice." (PMID 37497002, 2023). "Ki-67 LI and Bcl-2 EA in these tissues were lower than in samples from highly perfused enhancing tumor cores." (PMID 37345097, 2023). "On the other hand, the activation of OX40 can trigger additional anti-tumoral signaling promoting Bcl-xL and Bcl-2 expression, essential for long-term T-cell survival and elimination of the tumor suppressive activity of regulatory FOXP3+CD25+CD4+ T cells." (PMID 37719008, 2023). "Bcl-2 expression was considerably higher in tumor homogenates than in normal control tissue (P ≤ 0.01)." (PMID 36877301, 2023). "In the TCGA database, six patients bore a tumor with high expression of BCL2 mRNA, four of which carried a gene amplification." (PMID 37566004, 2023). "Rh2 achieves anti-tumor activity by inhibiting tumor cell migration, upregulating the pro-apoptotic gene Bax, downregulating the anti-apoptotic gene Bcl-2, and disrupting the HSP90A-CDC37 system in hepatocellular carcinoma cells." (PMID 37571224, 2023). "After targeting tumor tissue, the NPs exert antitumor effects by inhibiting the expression of Ki67/Bcl2 and enhancing tumor cell apoptosis." (PMID 36895440, 2023). "Our findings identify that CTSG has a tumor-inhibiting effect on CRC cells via controlling the activity of the Akt/mTOR/Bcl2 mediated anti-apoptotic signaling pathway." (PMID 37151875, 2023). "Compared with the CTX group, AGS-H and AGS-H synergistic CTX/2 treatment significantly inhibited the level of Bcl-2 in tumor tissues." (PMID 35445056, 2022). "Senescent tumor cells are known to be resistant to programmed cell death due to the upregulation of BCL2 and BCL-XL1,2,46,47." (PMID 35449130, 2022). "DOX can inhibit tumor growth mainly by inducing apoptosis and necrosis of tumor cells through mechanisms such as downregulating BCL-2 protein levels." (PMID 35725767, 2022). "The expression of Cleaved Caspase-3 was augmented while the expression of Bcl-2 was diminished in the tumor tissues after silencing HOTAIR." (PMID 35248107, 2022).
tumor (continued). "They found that SLNT treatment significantly inhibited tumor growth and increased the mouse tumor cells’ Bax/Bcl-2 protein expression ratio." (PMID 36298031, 2022). "Initially, BCL-2 was considered functionally unique amongst known tumor-promoting genes as it supports oncogenesis by preventing tumor cell death rather than driving tumor cell proliferation." (PMID 35349392, 2022). "Follicular lymphoma (FL) is a neoplasia of the germinal centers of follicles (centrocytes and centroblasts), with a follicular (nodular) pattern, and is frequently associated with the IGH/BCL2 translocation (t14;18)(q32;q21) that occurs in the bone marrow." (PMID 36358737, 2022). "Following up from these results, we showed that tigecycline and venetoclax acted synergistically against tumor xenografts derived from MYC/BCL2 double‐hit lymphoma." (PMID 36214609, 2022). "Along with Bax and Bcl-2, direct damage to tumour vasculature is also known to impact tumour response significantly when using USMB and chemotherapy." (PMID 35457210, 2022). "Decreased autophagic flux in ALK+ ALCL plays a role in drug resistance, and tumor cells are regulated in various ways that lead to inhibition of autophagy and crizotinib resistance including regulation of miRNAs and Bcl-2 expression." (PMID 35211406, 2022). "BCL2 has already been proposed as a therapeutic target as its pharmacological inhibition stops ASCL1‐dependent tumor growth." (PMID 35263037, 2022). "As it is well known, the expression of SFT markers STAT6, CD34, CD99 and bcl-2 can be lost in most aggressive tumours, following a process of dedifferentiation." (PMID 35864381, 2022). "Studies had shown that tumor cells with high expression of anti-apoptotic protein MCL-1 have primary resistance to the BCL-2 selective inhibitor." (PMID 35794605, 2022). "As most obvious hit, treatment strongly reduced tumor load in all 3 samples bearing BCL2-sgRNAs, indicating that knockout of BCL2 restored sensitivity of resistant PDX ALL-199 cells towards treatment in vivo." (PMID 36333584, 2022). "The imbalance in the expressions of Bax and Bcl-2 is involved in mitochondrial apoptosis, inducing the expression of cleaved caspase 3 and promoting tumor apoptosis." (PMID 35116094, 2022). "Since inhibiting the expression of anti-apoptotic proteins such as BCL-2, BCL-xL, and BCL-w displays a positive effect on tumor cell apoptosis, a series of anti-cancer reagents targeting BCL-2 have been developed in recent years." (PMID 35309994, 2022). "In Western blotting and IHC analysis, BH significantly induced the expression of FOXO3a in tumor tissue, whereas BH downregulated the expression of FOXO3a upstream regulators (NOTCH3, β-catenin) and Bcl-2 downstream genes in tumor tissue." (PMID 35463301, 2022). "The variations in the biological functions of BC cells were analyzed through CCK-8, transwell, western blotting, and xenograft experiments to observe cell viability, migration, levels of apoptosis-related proteins (Bax and Bcl-2), and tumor growth." (PMID 36299824, 2022). "These regions contained tumor-related genes, such as Muc16, Pik3, and Bcl2 in amplification regions and Hras, Notch1, Apc2, Ccnd1, Batf2, Dapk3, Smarca4, Traf2, Traf3, Cdk3, and Cdh4 in deletion regions." (PMID 36424557, 2022). "The antiapoptotic oncoprotein BCL2 plays a key role in the development and outcome of the tumor, lymphocyte growth, and immune system adjustment." (PMID 36276092, 2022). "Combination treatment suppressed tumor growth to a greater extent than either agent alone, indicating the requirement of both Mcl-1 and Bcl-2/Bcl-xL inhibition for effective ER+ tumor suppression." (PMID 35053443, 2022). "Changes in the ratio of anti-apoptotic members Bcl-2/MCL-1 also have an important impact on the efficacy of anti-tumor drugs in HCC." (PMID 35308206, 2022). "Endothelial cells overexpressing Bcl-2 (EC-Bcl-2) expressed significantly higher levels of E-selectin and exhibited enhanced tumor cell binding." (PMID 35992829, 2022).
tumor (continued). "It holds great promise in MM based on its induction of cell death in MM cell lines and primary tumor samples, especially those with t translocation, in which an increased dependency upon BCL-2 for MM cell survival has been determined." (PMID 36212502, 2022). "We have clarified that C1QBP promotes RCC cell hypoxanthine catabolism via up-regulating XDH, and apoptosis by modulating XDH mediated ROS generation and pro-apoptotic proteins caspase-3 and bax/bcl2, then affects tumor progression." (PMID 35693733, 2022). "The inhibition of LINC00461 reduced the expression of BNIP3 protein in tumor tissues, but also inhibited Ki67 and Bcl-2, and increased the level of Bax protein." (PMID 35783530, 2022). "Further comprehensive analysis revealed that the expression of BCL2, LEF1, PLK1, and BNIP3 was correlated with tumor mutation burden, microsatellite instability, drug sensitivity, and pathology stage." (PMID 35251139, 2022). "An alternative approach is to up-regulate pro-apoptotic proteins (e.g., Bim) that prime tumor cells (e.g., by pre-occupying or saturating anti-apoptotic proteins) for death induced by Bcl-2 inhibitors." (PMID 35574302, 2022). "Studies have shown that bryostatin-1 treatment initially increased the anti-apoptotic protein Bcl-2, but after a period of treatment, it decreased Bcl-2 through the ubiquitin degradation pathway, thus inducing the apoptosis of the tumor cells." (PMID 35736152, 2022). "Bax/Bcl-2 ratio was significantly decreased following CoCl2 treatment, which reduced tumor cell apoptosis." (PMID 35607406, 2022). "By implanting the DOX-loaded nanofibers after tumor resection, the sustainedly released DOX was able to inhibit tumor recurrence, however, which inevitably induced drug resistance via promoting Bcl-2 overexpression." (PMID 36297356, 2022). "We next classified senescent tumor cells in two subpopulations based on Bcl2 expression (Bcl2+ and Bcl2−)." (PMID 35449130, 2022). "The overexpression of Bcl-2 occurs in a variety of tumor cells, and Bcl-2 participates in the maintenance of tumor growth." (PMID 36297356, 2022). "Bcl-2-siRNA-loaded exosomes penetrated the cell membrane and delivered siRNA, resulting in apoptosis induction and reduced tumor growth." (PMID 35765040, 2022). "Peptide extracts from scorpion venom (PESV) have shown a number of pharmaco-logical properties that up-regulate caspase-3 and down-regulate Bcl-2 or modulate the activation of NF-kB to induce apoptosis, which inhibits various tumor cells." (PMID 35408621, 2022). "Surprisingly, both DOX and CHE increased Bcl-2 mRNA expression in tumor tissues of treated mice groups." (PMID 35881165, 2022). "Since Bcl-2 expression is limited in CRC tumor samples, we subsequently sought to understand the impact of nuclear MCL1 on the activity of the Bcl-xL inhibitor A-1331852." (PMID 35042842, 2022). "Except for E. brandianum, all extracts induced cellular autophagy in tumor cells with similar levels to that of rapamycin; but, only E. brandianum induced cellular apoptosis, likely through Bcl2 and BAX protein expressions." (PMID 35070357, 2022). "Increased proliferative capacity as well as expression of important factors for tumor growth and angiogenesis including Bcl-2, phosphorylated proteins ERK1/2, CXCR4, VEGF, and MDM2 mRNA was seen in those implanting with both MSC-EXOs and tumor cells." (PMID 36117723, 2022). "Induction of apoptosis (p < 0.05) coincided with suppression of Bcl2 and Hspa1a, and suppression of tumor angiogenesis coincided with suppression of F7, Fak3 and Frzb (involved in the regulation of growth and differentiation of certain cell types)." (PMID 35330327, 2022).